LAMA4 (laminin subunit alpha 4)
Description:
Binding to cells via a high affinity receptor, laminin is thought to mediate the attachment, migration and organization of cells into tissues during embryonic development by interacting with other extracellular matrix components.
Synonyms: LAMA3; CMD1JJ; LAMA4*-1
Tractability: Antibody: UniProt places it where antibodies can reach, with high confidence; its Gene Ontology location is reachable by antibodies, with high confidence; UniProt predicts a signal peptide or a membrane-spanning region; the Human Protein Atlas places it where antibodies can reach. Other modalities: an approved drug acts on it.
Gene: Protein-coding gene on chromosome 6 (112,106,077 to 112,254,939, reverse strand). Ensembl gene ENSG00000112769.
Subcellular location: Secreted, extracellular space, extracellular matrix, basement membrane; Secreted
Subcellular location (Human Protein Atlas): Cytosol; Plasma membrane; Predicted to be secreted
Pathways (Reactome):
Extracellular matrix organization: ECM proteoglycans; Formation of the dystrophin-glycoprotein complex (DGC); Laminin interactions; Non-integrin membrane-ECM interactions
Developmental Biology: Developmental Lineage of Pancreatic Ductal Cells
Disease: Attachment of bacteria to epithelial cells
Signal Transduction: MET activates PTK2 signaling
Gene Ontology:
Molecular function: extracellular matrix structural constituent; signaling receptor binding
Biological process: negative regulation of cold-induced thermogenesis; nervous system development; signal transduction; cell adhesion; regulation of cell adhesion; regulation of cell migration; regulation of embryonic development
Cellular component: basement membrane; extracellular exosome; extracellular matrix; extracellular region; laminin-14 complex; laminin-8 complex; laminin-9 complex; plasma membrane; synapse; neuromuscular junction; synaptic cleft
Genetic constraint (gnomAD): Loss-of-function variants: 105 observed, 174.27 expected, observed/expected ratio (o/e) 0.6, 90% interval 0.51 to 0.71. The upper end of that interval is the gene's LOEUF score, 0.71, which puts it in group 2 of 6, group 1 being the genes least tolerant of losing a copy. Missense variants: 1,853 observed, 2,110 expected, observed/expected ratio (o/e) 0.88, 90% interval 0.84 to 0.91. Synonymous variants: 698 observed, 782.27 expected, observed/expected ratio (o/e) 0.89, 90% interval 0.84 to 0.95.
Gene-disease validity (ClinGen):
ClinGen rates the evidence that LAMA4 causes each of these diseases.
dilated cardiomyopathy 1JJ (autosomal dominant): Limited. Any familial isolated dilated cardiomyopathy in which the cause of the disease is a mutation in the LAMA4 gene.
Homologues: Orthologues: chimpanzee LAMA4 (99% identical), macaque LAMA4 (98% identical), pig LAMA4 (91% identical), guinea pig LAMA4 (88% identical), mouse Lama4 (88% identical), rat Lama4 (88% identical), rabbit LAMA4 (86% identical), dog LAMA4 (86% identical), tropical clawed frog lama4 (58% identical). Paralogues in human: LAMA3 (30% identical), LAMA5 (28% identical), LAMA2 (23% identical), LAMA1 (20% identical), USH2A (18% identical), HSPG2 (17% identical), AGRN (12% identical), LAMB1 (9% identical), LAMB2 (9% identical), LAMC3 (9% identical), LAMC1 (8% identical), LAMB4 (8% identical), and 15 more.
Diseases named in the same sentence as LAMA4 in open-access papers:
LAMA4 is named in the same sentence as 107 diseases in open-access papers, as found by Europe PMC text mining. Sharing a sentence is not in itself a finding about the gene and the disease. The quoted sentences say what the papers report.
renal cell carcinoma (12 papers, 2017 to 2026). "For instance, miR-200b downregulated LAMA4 expression and suppressed renal cell carcinoma metastasis." (PMID 36539799, 2022). "LAMA4 overexpression induced cell migration in renal cell carcinoma via activation of the ILK/FAK/ERK pathway." (PMID 34414238, 2021). "High expression levels of LAMA4 were also shown to predict poor survival in renal cell carcinoma." (PMID 34414238, 2021). "Although the role of hsa-miR-200b has not been clear in bladder cancer, it seems particularly significant in renal cancer: it is often downregulated and may suppress metastasis by targeting LAMA4 in renal cell carcinoma." (PMID 33806327, 2021). "One study has found that melanoma cell adhesion molecule (MCAM) and its extracellular matrix interaction partner laminin alpha 4 (LAMA4), which have emerged as the genes most consistently expressed in blood vessels, can predict poor survival in renal cell carcinoma." (PMID 28029655, 2017). "These links to cancer include recent studies which found that LAMA4 and MCAM (melanoma cell adhesion molecule) are highly enriched in tumor blood vessels in renal cell carcinoma and colorectal carcinoma." (PMID 32571313, 2020). "Genes such as LAMA4, LAMA5, and C1QTNF6 were involved in angiogenesis in many cancer types such as renal cell carcinoma, colorectal cancer, and hepatocellular carcinoma, but these genes may be linked with angiogenesis in GBM." (PMID 31137733, 2019). "LAMA‐4 is not expressed in normal vascular endothelial cells; both Angiopietin‐2 and LAMA‐4 are expressed in renal cell carcinoma and have been reported as prognostic factors." (PMID 39440923, 2024).
Obesity (10 papers, 2014 to 2025). Accumulation of substantial excess body fat. "In conclusion, we show an association of LAMA4 expression with parameters of fat accumulation and distribution in patients with obesity." (PMID 37893179, 2023). "Specifically, we sought to explore the overall association between LAMA4 expression and clinical parameters in a cross-sectional cohort primarily comprised of individuals with obesity." (PMID 37893179, 2023). "Our results support significant associations between obesity related clinical parameters and elevated LAMA4 expression in humans." (PMID 37893179, 2023). "Examining the CSC data for obesity-related signals associated with LAMA4 expression we observed several correlations with a p < 0.05 and absolute Spearman’s correlation coefficient |ρ| ≥ 0.1 (not adjusted for FDR)." (PMID 37893179, 2023). "Nevertheless, our findings support previous reports which associated LAMA4 expression with obesity and increased fat mass." (PMID 37893179, 2023). "When analyzing the BSC RNA sequencing data to identify obesity-related signals associated with LAMA4 expression, we found several correlations that met the statistical criteria of p < 0.05 and |ρ| ≥ 0.1 (not adjusted for FDR)." (PMID 37893179, 2023). "Lastly, in addition to investigating LAMA4 in obesity, we studied the effect of weight loss on expression of LAMA4 in sWAT." (PMID 34394003, 2021). "Mice with a null mutation in the laminin α4 (LAMA4) gene (KO) exhibit resistance to obesity and enhanced expression of thermogenic fat markers in white adipose tissue (WAT)." (PMID 33686208, 2021). "Further studies should clarify the mechanisms underlying this association to target LAMA4 effectively as a potential therapy for obesity." (PMID 34394003, 2021). "From these results we propose a significant association between obesity and elevated LAMA4 expression in humans, as well as in mouse models of obesity." (PMID 34394003, 2021). "In addition to its potential relevance in obesity, LAMA4 has been linked to the prognosis of gastric cancer and immune cell infiltration, suggesting LAMA4 as a therapeutic target for these conditions." (PMID 37893179, 2023). "Our data are indicative of associations between LAMA4, obesity, and adipose tissue function, but further studies are required to substantiate whether LAMA4 is mechanistically linked to AT dysfunction and fat mass." (PMID 37893179, 2023). "Finally, by combining Gene Set Enrichment Analysis (GSEA) with a comprehensive literature review, we identified statistically significant associations between LAMA4 expression and obesity parameters." (PMID 37893179, 2023). "Overall, these findings describe a significant association between LAMA4 and obesity in humans." (PMID 34394003, 2021). "Similar to LAMA4 and LAMB1, LAMC1 is closely related to adipogenic differentiation, with significant overexpression in obesity-associated samples." (PMID 40130165, 2025). "LAMA4 is considered a negative regulator of adipocyte differentiation, showing increased levels in both obese populations and mouse models of obesity." (PMID 40130165, 2025). "Laminin isoform alpha 4 (LAMA4) expression, a key component of the basement membrane, is higher in patients with obesity and in vivo obesity models." (PMID 40847127, 2025). "Laminin α4 (LAMA4) is one of the main structural adipocyte basement membrane (BM) components that is upregulated during adipogenesis and related to obesity in mice and humans." (PMID 37893179, 2023). "Compared to wildtype mice, LAMA4 −/− mice exhibit higher energy expenditure, decreased weight gain, and protection against diet-induced obesity and insulin resistance." (PMID 37893179, 2023). "Analyses of the adipocyte surface proteome revealed an increased abundance of LAMA4 on the surface of adipocytes, both in diet-induced obesity (DIO) and in ob/ob mice." (PMID 37893179, 2023).
Obesity (continued). "Our work offers one of the first references for understanding the meaning of LAMA4 expression specifically in relation to obesity based on large-scale RNA-seq data." (PMID 37893179, 2023). "Our aim was to explore the relationship between LAMA4 and clinical obesity markers, gender, weight reduction after bariatric surgery, and insulin resistance or sensitivity." (PMID 37893179, 2023). "Adipose tissue LAMA4 levels are increased in human and murine obesity, though the consequences of this are unclear." (PMID 36140178, 2022). "Whole-body LAMA4 deletion is associated with decreased fat mass in mice, while obese mice and humans with obesity exhibit increased adipose tissue levels of LAMA4." (PMID 36140178, 2022). "Data from studies on Lama4−/− mice have advanced our understanding of adipose tissue LAMA4 and its regulation in obesity." (PMID 36140178, 2022). "We demonstrate a parallel upregulation of Lama4 in male mice fed HFD and LAMA4 in female human subjects with obesity compared to lean controls and verify that this upregulation is reflected at both the mRNA and protein level." (PMID 34394003, 2021). "We highlight an important relationship between LAMA4 and obesity in both mice and humans, suggesting that laminins play a critical role in obesity development in human subjects." (PMID 34394003, 2021). "The unique elevation of LAMA4 in obese sWAT suggests that this chain assumes a specialized role in the adipocyte microenvironment during obesity." (PMID 34394003, 2021). "In this investigation we characterize the relationship between obesity and LAMA4 in both mice and humans and illustrate the important role of this ECM protein in adipose tissue across models." (PMID 34394003, 2021). "Future investigations should compare LAMA4 expression in male and female subjects with obesity to determine if there are any differences based on sex." (PMID 34394003, 2021). "We verified by immunofluorescence staining that extracellular LAMA4 protein was also significantly increased in the subjects with obesity pre-surgery compared to the controls (p<0.05)." (PMID 34394003, 2021). "sWAT from human subjects with obesity also showed significantly higher LAMA4 mRNA (p<0.01) and LAMA4 protein expression (p<0.05) than controls." (PMID 34394003, 2021). "In this study, we confirm the correlation between obesity and increased LAMA4 in a mouse model and show that human sWAT displays a similar trend." (PMID 34394003, 2021). "The sWAT samples from subjects with obesity pre-surgery displayed 4-fold greater LAMA4 expression than the control subjects (p<0.01)." (PMID 34394003, 2021). "In this study we aim to describe the relationship between LAMA4 and obesity in both mouse and human models and determine the effect of weight loss on LAMA4 expression." (PMID 34394003, 2021). "To study the relationship between Lama4 and obesity, we placed 8-week-old WT male mice on regular chow diet (RCD) or 45% high fat diet (HFD) for 8 weeks." (PMID 34394003, 2021). "The Lama4−/− mice were found to be resistant to age-related and diet-induced obesity, and exhibited a depot-specific change in adipose tissue structure, volume and function." (PMID 25310607, 2014). "To further investigate the relationship between LAMA4 and clinical markers of obesity, we conducted an analysis of LAMA4 gene expression in SC and VIS AT depots across a total of 1586 individuals from three distinct clinical cohorts of the Leipzig Obesity BioBank (LOBB) using RNA sequencing data." (PMID 37893179, 2023). "Moreover, we focused on investigating the potential differences in LAMA4 expression between metabolically healthy and unhealthy individuals with obesity, as well as changes in LAMA4 expression in response to extensive weight loss following bariatric surgery." (PMID 37893179, 2023). "Previous research has revealed a significant upregulation in LAMA4 expression in obesity." (PMID 37893179, 2023).
Obesity (continued). "While it is not fully understood what role LAMA4 may play in aggravating obesity in humans, it is likely that LAMA4 is both deposited in elevated levels in response to obesity and can influence adipocyte function and pathways relating to lipid metabolism." (PMID 34394003, 2021). "Although preliminary murine studies have suggested that obesity correlates with increased LAMA4 expression, it was undetermined whether this finding is true in lean and obese humans." (PMID 34394003, 2021). "Taken together, the weight loss and in vitro data suggest that the LAMA4-obesity connection is complex and is not modulated rapidly." (PMID 34394003, 2021). "While these results suggest that LAMA4 may be an important regulator of adipocyte function, its clinical relevance to various models of obesity remains poorly characterized." (PMID 34394003, 2021). "Furthermore, our group has shown that the silencing of Lama4 in mice leads to the reduced adipose mass accumulation and protection from obesity on a HFD." (PMID 34394003, 2021). "We also conclude that short-term weight loss in DIO mice and human subjects with obesity does not downregulate LAMA4 expression." (PMID 34394003, 2021). "Importantly—in a metabolic context—LAMA4 knock-out mice resist diet-induced obesity (DIO), show reduced visceral fat expansion, and increased energy expenditure, suggesting that LAMA4 promotes metabolic dysfunction in obesity." (PMID 33854178, 2021). "While the results of this study suggest that LAMA4 is significantly associated with obesity, we still do not fully understand the mechanisms underlying this observation." (PMID 34394003, 2021). "Next, we compared the expression of LAMA4 in the subjects with obesity 3 months after bariatric surgery to determine if short term weight loss could reverse the observed upregulation of LAMA4." (PMID 34394003, 2021). "As with other laminin chains, LAMA4 is implicated in ECM remodeling in several tissue types including muscle and various tumor types, however it is only just beginning to be associated with adipose tissue remodeling and dysfunction in obesity." (PMID 34394003, 2021). "In human obesity, LAMA4 has only been investigated to the extent of depot specific comparisons." (PMID 34394003, 2021). "Preliminary dietary studies showed that female mice placed on HFD did not gain significant weight during the dietary study timeline and therefore were not a good model to study the association of Lama4 and obesity." (PMID 34394003, 2021). "We found that short-term weight loss was not sufficient to reduce LAMA4 expression from the high levels seen in HFD fed mice or human subjects with obesity." (PMID 34394003, 2021). "Interestingly, weight loss in obese mice and humans does not decrease LAMA4 expression, indicating potential lasting effects of obesity." (PMID 40847127, 2025). "In doing so, we hope to uncover how LAMA4 may be targeted effectively in therapies for obesity." (PMID 34394003, 2021). "Most recently, adipose tissue LAMA4 levels were found to be increased in HFD-fed C57BL/6J mice and adipose tissue of people with obesity." (PMID 36140178, 2022). "As Lama4 expression was significantly augmented in HFD fed mice, we wanted to understand if this trend applied to human obesity." (PMID 34394003, 2021). "AT LAMA4 expression was not significantly different between subjects with or without obesity, metabolically healthy versus unhealthy, and obesity before versus after short-term weight loss." (PMID 37893179, 2023). "Furthermore, our study observed several differentially regulated EFP proteins in the AE group that can mitigate diet-induced obesity, such as the upregulated PRDX5 as well as the downregulated LAMA4, S27A1, and HS12A, as reported in previous studies." (PMID 36982812, 2023). "In non-diabetic humans with obesity, LAMA4 levels were found to be increased in the secretome of visceral WAT (vWAT) adipocytes compared to sWAT, however the opposite trend has been reported in mice." (PMID 34394003, 2021).
Obesity (continued). "We have previously shown that laminin, alpha 4 (Lama4) knockout in mice leads to resistance to adipose tissue accumulation; however, the relationship between LAMA4 and obesity in humans has not been established." (PMID 34394003, 2021). "This time range was selected because it is prior to any statistically significant weight differences between Lama4−/− and control animals, allowing for the examination of adipose tissue function without confounding results due to obesity." (PMID 25310607, 2014). "However, at least in adults, LAMA4 expression does not seem to be directly regulated by alterations in fat mass, obesity status, or metabolic health." (PMID 37893179, 2023). "A more recent study reported an overall upregulation of LAMA4 in SC white AT in both high-fat-diet (HFD)-fed mice and a human cohort of ten women with obesity, but without diabetes, compared to three healthy, lean women at the gene expression level." (PMID 37893179, 2023). "The density of LAMA4 in the ECM of obese adipose was about 30% greater than in control adipose, suggesting that the adipocytes in sWAT of subjects with obesity do in fact produce and deposit more LAMA4 than adipocytes from subjects without obesity." (PMID 34394003, 2021).